Y_RNA (Y RNA )
Gene: Miscellaneous RNA gene on chromosome 16 (14,915,457 to 14,915,556, reverse strand). Ensembl gene ENSG00000207425.
Homologues: Orthologues: chimpanzee Y_RNA (98% identical), macaque Y_RNA (93% identical), dog Y_RNA (80% identical), pig Y_RNA (80% identical). Paralogues in human: Y_RNA (100% identical), Y_RNA (98% identical), Y_RNA (84% identical), Y_RNA (83% identical), Y_RNA (82% identical), RNY3 (81% identical), Y_RNA (81% identical), RNY3P1 (80% identical), RNY3P4 (80% identical), Y_RNA (80% identical), RNY3P11 (79% identical), Y_RNA (79% identical), and 92 more.